POTEM (POTE ankyrin domain family member M)
Synonyms: POTE14beta; P704P; ACT
Tractability: PROTAC: ubiquitination databases record sites on it.
Gene: Protein-coding gene on chromosome 14 (18,967,434 to 19,003,752, forward strand). Ensembl gene ENSG00000222036.
Genetic constraint (gnomAD): Loss-of-function variants: 0 observed, 8.61 expected, observed/expected ratio (o/e) 0, 90% interval 0 to 0.35. That is too few expected variants to judge how well the gene tolerates losing a copy. Missense variants: 17 observed, 100.77 expected, observed/expected ratio (o/e) 0.17, 90% interval 0.11 to 0.25. Synonymous variants: 8 observed, 30.02 expected, observed/expected ratio (o/e) 0.27, 90% interval 0.16 to 0.48.
Homologues: Paralogues in human: POTEG (99% identical), POTEH (99% identical), POTEI (91% identical), POTEF (90% identical), POTEE (90% identical), POTEB3 (88% identical), POTEC (87% identical), POTED (86% identical), POTEJ (84% identical), POTEB (82% identical), POTEB2 (82% identical), POTEA (55% identical), and 2 more.
Diseases named in the same sentence as POTEM in open-access papers:
POTEM is named in the same sentence as 2 diseases in open-access papers, as found by Europe PMC text mining. Sharing a sentence is not in itself a finding about the gene and the disease. The quoted sentences say what the papers report.
cancer (1 paper, 2014). A tumor composed of atypical neoplastic, often pleomorphic cells that invade other tissues. "While three of the chimeras (ACTB->POTEM, ACTB->POTEE and SP100->HMGB1) have been found in normal population, three of the chimeras (C2orf27A->NBEA, HILPDA->EFCAB3, FARSB->TRIM61) were previously identified only in cancer samples." (PMID 25133550, 2014).
POTEM also shares sentences with these, for which no sentence is quoted: tumor (1 paper).